MDM2 (MDM2 proto-oncogene)
Diseases named in the same sentence as MDM2 in open-access papers (continued):
Sharing a sentence is not in itself a finding about the gene and the disease.
cancer (continued). "Additionally, MDM2 stabilizes oncogenic factors such as E2F1 and STAT5 by preventing their degradation, reinforcing cancer cell survival." (PMID 41170373, 2025). "Additionally, the top hub genes identified in the PPI network of FZD4 miRNA targets, including MYC, EGFR, MDM2, and CDK1, were also involved in many aspects of cancer progression." (PMID 40667070, 2025). "In alignment with MDM2, NCL is frequently overexpressed in various cancer types, and it exhibits a dynamic shuttling mechanism between the nucleus, cytoplasm, and cell surface, as well as serving as a membrane-anchored receptor in both tumor cells and endothelial cells of angiogenic blood vessels." (PMID 40866949, 2025). "Next, given its established role in cancer, we focused on RNA editing events in the 3’UTR of MDM2." (PMID 40381037, 2025). "Finally, we discuss the current landscape in the development of MDM2 and MDM4 inhibitors for cancer therapy." (PMID 39960347, 2025). "For instance, genes like NOTCH2, IFNGR2, and MDM2 are upregulated in the Pathways in Cancer—specifically, NOTCH2 and IFNGR2." (PMID 40621499, 2025). "Milademetan is an Mdm2 inhibitor that has demonstrated therapeutic efficacy in phase Ib/II studies in patients with intimal sarcoma, an extremely rare cancer with no standard care." (PMID 40295432, 2025). "Several new-generation MDM2 inhibitors have been developed, including RG7388, HDM201, AMG232, DS-3032, ASTX295, and MI-77301, which have been shown to reduce cancer cell viability and proliferation in preclinical models, including leukemia and lymphoma cells." (PMID 39858058, 2025).
cancer (continued). "In contrast to AD‐04, MDM2 antagonists (SAR405838) did not affect sVEGF neither in activated fibroblasts nor cancer cells." (PMID 38602256, 2024). "Sirt1 suppression itself does not lead to cancer cell death, requiring Sirt6- and MDM2-mediated downregulation to induce an anti-cancer effect." (PMID 38254877, 2024). "Interaction with the mentioned proteins might destabilise AKT1, MDM2, and PRKN signalling pathways, which control cancer cells’ survival, proliferation, invasion, apoptosis, and angiogenesis, making the combined drug’s therapeutic effect promising." (PMID 39204341, 2024). "Palbociclib did not significantly reduce the expression of the MDM2 gene in triple negative (MDA-MB-231) cancer cells; however, a decrease was observed in luminal A (MCF-7) cells." (PMID 39116089, 2024). "On the basis of the fact that MDM2 overexpression did not affect cancer cell proliferation, we sought to determine the apoptotic state in Osimertinib resistant NSCLC cells." (PMID 39543744, 2024). "Conversely, in male cancer cells, TSPYL2 is still ubiquitinated by MDM2 and degraded." (PMID 36918555, 2023). "No variants were evident in the key cancer genes PTEN, MTOR, AKT1, TSC1/2 or MDM2, or in genes encoding components of PI3K." (PMID 37079639, 2023).
cancer (continued). "Both MDM2 and MDM4 proteins are overexpressed in a range of human cancers." (PMID 36624687, 2023). "While the targeting of P-TEFb augments apoptosis by anti-metabolite 5-fluorouracil, it switches the fate of cancer cells by the non-genotoxic MDM2 inhibitor Nutlin-3a from cell-cycle arrest to apoptosis." (PMID 36727434, 2023). "Furthermore, we observed a positive correlation between the content of MDM2 p60 and CASP2 activity in ACP52C resistance in cancer cells." (PMID 37845006, 2023). "In addition to the inhibitory function on cell migration and cancer metastasis, MTBP has also been proposed to play roles in origin firing for DNA replication, mitotic progression, MDM2 stabilization, regulation of Myc, and promotion of cancer progression." (PMID 37760565, 2023). "Low MDM2 and high PUMA levels were found in cancer patients as favorable prognostic features." (PMID 37373017, 2023). "In normal cells, the overexpression of MDM2 can induce G1 phase arrest, but in many cancer cells, including cells overexpressing MDM2, the arrest in the G1 phase is not apparent." (PMID 36770809, 2023).
cancer (continued). "Similarly, the potent in vivo and in vitro anti-cancer effects of ALRN-6924 through the dose- and time-dependent dual inhibition of MDM2/MDMX have been observed in various preclinical models." (PMID 36465350, 2022). "Given the E3 ubiquitin ligase property of both MDM2 and RNF6 in cancer metabolism, GLA might exert its antitumor effect on GC cells by blocking MDM2 and RNF6-mediated deregulated ubiquitination processes." (PMID 35814430, 2022). "Although Nutlin‐3a is known to induce apoptosis and inhibit proliferation of cancer cells, this MDM2 inhibitor did not alter the apoptotic and proliferative phenomena in the liver of CDAHFD‐fed mice." (PMID 35524581, 2022). "The advantages of ATSP-7041 and ALRN-6924 dual inhibition of MDMX and MDM2 were shown by head-to-head comparison with selective MDM2 inhibitors, RG7112 and RG7388, in cancers that overexpress MDMX, where these dual-peptide-based inhibitors showed superior activity." (PMID 36678521, 2022). "Among Akt downstream effectors, Mdm2, IKKβ, PAK1 and Rho GTPases may represent potential targets for human cancers." (PMID 36180910, 2022).
cancer (continued). "A panel of small-molecule inhibitors of MDM2, including RG7112, RG7388, AMG-232, APG-115, BI-907828, CGM097, sirmadlin, milademetan, SAR405838, MK-8242, PRIMA1, and APR-246, is undergoing clinical trials investigating their therapeutic effects on cancers." (PMID 36499442, 2022). "Among the target compounds, one spirooxindole-based hydroxamic acid 11b exhibited comparable inhibitory activities among MDM2 and HDAC, it also possessed good in vitro activity toward the tested three cancer cells, especially MCF-7, reaching the IC50 value of 1.37 ± 0.45 μM." (PMID 35992773, 2022). "Many inhibitors of RING finger E3 ligases have demonstrated considerable therapeutic potential in preclinical models and clinical trials of cancer immunotherapy or combination therapy, among which the most studied inhibitors include the IAP family, MDM2, pVHL, Skp2, and β-TrCP." (PMID 34943817, 2021). "HSPs, MDM2/4, and the CHIP chaperone are among these regulators and might be possible targets for anti-cancer therapeutics." (PMID 34359820, 2021). "We performed analogous IP-MS/MS experiments and Genoppi analyses of two more proteins (MDM2 and PTEN) that are also hypothesized to have divergent functions in cancer and neurodevelopment." (PMID 33972534, 2021). "In malignant tumors, a study using second-generation sequencing found that the amplification rate of MDM2/4 was about 3.9% (6/155), and that the TTF of all patients with MDM2/4 amplification receiving immunotherapy was less than 2 months." (PMID 34290608, 2021). "For more extensive reviews on targeting MDM2 and MDMX in cancer therapy, see." (PMID 34307171, 2021). "Like Mdm2, COP1 has been reported to be highly expressed in different human cancers." (PMID 33670160, 2021).